POLE (DNA polymerase epsilon, catalytic subunit)
Diseases named in the same sentence as POLE in open-access papers (continued):
Sharing a sentence is not in itself a finding about the gene and the disease.
colon carcinoma (continued). "In the family described in the present study, carriers generally have multiple colorectal adenomas and cancer of colon, pancreas, ovaries and small intestine which represents an important broadening of the tumour spectrum of POLE mutation carriers." (PMID 25860647, 2015). "The POLE variant seen in our patient, P436R, has been documented in a handful of endometrial and colon cancer cases and has been described to have a high MutationAssessor-predicted functional impact score (MASS PIFS) and a damaging effect on other predicted functional impact scores." (PMID 37239414, 2023). "Notably, we observed that mutations in KRAS, PIK3CA, CREBBP, FAT1, PKHD1, ARID2, and POLE were specifically enriched in right-site colon cancers in both our cohort and the validation cohort." (PMID 36439454, 2022). "TMB can be used as an important complementary biomarker, such as when combined with MSI, and for identifying other significant gene mutations; it was found, that some MSS colon cancer patients with high TMB had polymerase epsilon (POLE) mutation, and they responded well to immunotherapy." (PMID 36483562, 2022). "Previous patients with a germline POLE mutation have presented with MSI‐H colon tumors." (PMID 33369189, 2021). "Interestingly, one additional subgroup of colon cancers with increased (intraepithelial) CD8+ TILs comprises those with pathogenic somatic mutations of POLE." (PMID 33353162, 2020). "However, a recent paper confirmed the association of colon cancer harboring somatic mutations of the exonuclease domain of POLE with infiltrating CD8+ cells and excellent outcome." (PMID 33353162, 2020). "Together, this suggests that POLE-mutated colon cancer may also respond well to the PD-1 blockade." (PMID 37239414, 2023). "If this study meets the primary endpoint, using avelumab in the adjuvant setting following standard chemotherapy would become the standard of care for patients with dMMR/MSI-H and/or POLE exonuclease domain mutant colon cancers." (PMID 32079623, 2020). "Metastatic dMMR colon cancers are highly sensitive to immune checkpoint inhibition, and recent data show POLE-mutant tumours are similarly responsive." (PMID 32079623, 2020). "We are recruiting patients with completely resected, stage III colon cancer confirmed to have dMMR/MSI-H, locally or POLE exonuclease domain mutation on central testing." (PMID 32079623, 2020). "10%–15% of early-stage colon cancers harbour either deficient mismatch repair (dMMR), microsatellite instability high (MSI-H) or POLE exonuclease domain mutations, and are characterised by high tumour mutational burden and increased lymphocytic infiltrate." (PMID 32079623, 2020). "Four out of the five patients with a POLE-mutated EMCA and a family history of colon cancer showed a P286R mutation." (PMID 30917185, 2019). "For the cancer susceptibility genes identified in the cohort that are not involved in LS, we found several genes implicated in the hereditary colorectal cancer landscape: APC, MUTYH, POLE, POLD1, and BLM, as well as genes resulting in an increased risk of colon cancer as CHEK2." (PMID 36232851, 2022). "Given the molecular mechanism of PPAP in carcinogenesis and the characteristics of the MSI‐H colon cancers previous reported, the identified POLE PV may be the etiology of this identified ovarian tumor with MMR‐D." (PMID 33369189, 2021). "These can be attributed to mutations in the POLE gene that cause DNA polymerase ε deficiency: we find an increased overall mutation rate, a very high proportion of T[C >A]T and T[C >T]G mutations and a high contribution of COSMIC signature 10 in six out of 42 colon cancer samples." (PMID 29673314, 2018).
colon carcinoma (continued). "Of the three patients other than our patient, one was diagnosed with GPV in POLE, and two were diagnosed with GPVs in POLD1; all of them had a history of colon cancer." (PMID 40741356, 2025). "We compared the mutation spectrum of our aggregated HT115 branch variant SNV call set with mutation spectra derived from tumor-normal whole-genome sequencing of group A POLE colon tumors (samples with mutant POLE but not mutant POLD1) generated by the TCGA Research Network and found high similarity." (PMID 30459213, 2018). "Tumor exome sequencing performed in the MMR-deficient colon cancer developed by the POLD1 c.230delC (p.Pro77Leufs*92) carrier revealed that ~85% of the signatures’ contribution corresponded to MMR deficiency and no representation of POLE/D1-associated signatures." (PMID 32792570, 2020).
polyposis (30 papers, 2014 to 2025). "Germline missense PV affecting proofreading capabilities of POLE/POLD1 are associated with increased EC risk as a part of polymerase proofreading-associated polyposis, but the importance of germline POLD1/POLE truncating variants remains rather elusive." (PMID 37153042, 2023). "Our results highly support the convenience of NGS multigene panels for attenuated polyposis genetic screening and reveals POLE frameshift variants as a plausible susceptibility mechanism for AAP." (PMID 31285513, 2019). "Since this seminal discovery, several publications have found evidence supporting roles for additional germline POLD1 and POLE mutations in cancer predisposition, in which carriers typically develop multiple adenomas, polyposis, CRC, and/or EC." (PMID 28117753, 2017). "A 14-year-old boy with polyposis and rectosigmoid carcinoma was found to have inherited a POLE-V411L mutation." (PMID 28117753, 2017). "In a 14-year-old boy with polyposis and rectosigmoid carcinoma, we identified a novel POLE germline mutation, p.(Val411Leu), previously found as recurrent somatic mutation in ‘ultramutated’ sporadic cancers." (PMID 27573199, 2017). "Germline mutations of POLD and POLE were shown to predispose individuals to a polyposis-phenotype with large adenomas similar to that observed in MUTYH-associated polyposis or early onset and multilocated cancers, respectively." (PMID 25124163, 2014). "However, it is remarkable that through all NGS efforts, only few novel high-penetrant risk genes for hCRC and polyposis have been established in the past decade, such as POLE, POLD1 and NTHL1." (PMID 33228212, 2020). "Therefore, this POLE mutation most likely is the cause of the polyposis and early onset rectosigmoid cancer in the patient." (PMID 27573199, 2017). "This is the youngest reported cancer patient with polymerase proofreading-associated polyposis indicating that POLE mutation p.(Val411Leu) may confer a more severe phenotype than previously reported POLE and POLD1 germline mutations." (PMID 27573199, 2017). "Second, several repair-related genes during DNA replication are also thought to be associated with polyposis, such as MUTYH4, NTHL124, MSH325, POLE, and POLD126–28." (PMID 33628596, 2021). "It is worth mentioning that we previously evaluated the prevalence of the recurrent mutations POLE c.1270C>G, p.(Leu424Val) and POLD1 c.1433G>A, p.(Ser478Asn) in a cohort of Dutch index patients with multiple polyps or familial CRC." (PMID 30827058, 2019). "Recently, pathogenic variants in the POLE and POLD1 gene were found to explain a small portion of polyposis cases." (PMID 25604157, 2015). "We identified no pathogenic variants in more recently discovered polyposis predisposition genes (POLE, POLD1 or NTHL1), rendering the presence of such founder variants rare." (PMID 39516274, 2024). "Moreover, mutations in polymerase proofreading–associated syndrome involving POLE and POLD1 constitute 0.3–0.7% of familial cancer cases when only CRC and polyposis are considered." (PMID 35751785, 2022). "Variants in the exonuclease domain of the polymerase proofreading genes POLE and POLD1 cause polymerase proofreading-associated polyposis, which is a dominant-inheritance and high-penetrance hereditary syndrome conferring a predisposition to attenuated colorectal polyposis and early-onset CRC." (PMID 32973888, 2020). "In a cohort of patients with polyposis or who fulfilled Amsterdam criteria, POLE mutations were noted in 1.5%, whereas a population-based German cohort reported a considerably higher rate of mutations via classic Sanger Sequencing (12.3%)." (PMID 28492495, 2017). "A few polyposis patients have been linked to other genes, such as SMAD4, BMPR1A, POLE and POLD1." (PMID 25604157, 2015). "Therefore, it is plausible that POLE and NTHL1 co-occurring truncating variants may have a synergistic effect leading to a polyposis predisposition in high division tissues such as the colon epithelium." (PMID 31285513, 2019).
polyposis (continued). "Recent studies have proposed the term “POLE/POLD1-associated tumor syndrome” to encompass a broader clinical spectrum beyond classical PPAP, recognizing that some patients carrying germline mutations in POLE or POLD1 may develop tumors without evidence of polyposis." (PMID 40661943, 2025).
Lynch syndrome (24 papers, 2014 to 2026). An autosomal dominant hereditary neoplastic syndrome characterized by the development of colorectal carcinoma and a high risk of developing endometrial carcinoma, gastric carcinoma, ovarian carcinoma, renal pelvis carcinoma, and small intestinal carcinoma. "Polymerase proof-reading associated polyposis and Lynch-like syndrome are inherited cancer susceptibility syndromes associated with germline POLE mutations." (PMID 36479248, 2022). "Although the prevalence of germline monoallelic POLE pathogenic variant is low, they identify distinct phenotypes with a broad tumor spectrum, in contrast to other genetic disorders such as Lynch syndrome or familial adenomatous polyposis." (PMID 35812186, 2022). "Among the cases with MSI, the majority of them are LS cases with a mutation in DNA repair (MMR) genes detected, although MSI may also be observed in sporadic CRC due to somatic alteration in MMR genes or cases of Lynch-like syndrome caused by mutation of other genes (POLE/POLD1)." (PMID 36553592, 2022). "Given that POLE gene mutations can induce loss of MMR protein expression, this case was diagnosed as Lynch-like syndrome attributed to a POLE pathogenic mutation." (PMID 41278281, 2025). "POLE mutation and microsatellite instability (MSI) are strong prognostic markers, with POLE mutation showing good prognosis and MSI is linked with Lynch syndrome." (PMID 40940815, 2025). "The study enrolled patients who had germline replication repair deficiency, such as Lynch syndrome, constitutional MMRD, or POLE mutation." (PMID 39204096, 2024). "These mutations can occur in genes like POLE and POLD1, as well as in MMR genes, which are associated with Lynch syndrome." (PMID 39204096, 2024). "This is the first report of a CMMRD-like Lynch syndrome case with a pediatric ultra-hypermutated GBM following a confirmed somatic second hit of a MMR and POLE mutation." (PMID 31604779, 2019). "Despite the unexpected diagnosis of Lynch syndrome as the underlying cancer susceptibility disorder, the mutational profile is still consistent with MMR first and POLE second in the tumor-initiating astrocyte." (PMID 31604779, 2019). "We interpret the case as a patient with Lynch syndrome with two secondary, non-pathogenic POLE mutations, not included in the list of mutations detected by the Modaplex POLE/POLD1 Mutation Analysis Kit." (PMID 37874375, 2023). "Conversely, we reported a child with “POLE-Lynch syndrome” carrying a de novo PMS2 DCV and inherited POLE DCV, manifested by an aggressive medulloblastoma with a unique genomic signature." (PMID 39546165, 2024). "The case was reinterpreted as a patient with Lynch syndrome, and a MSH6 germline mutation, and two non-pathogenic POLE mutations, not included in the list of mutations identifiable by the test." (PMID 37874375, 2023).
endometrioid carcinoma (21 papers, 2017 to 2025). "The POLE mut subtype accounts for approximately 6%–8% of EC cases, mainly involves endometrioid carcinoma, is prevalent among young women, and is associated with a good prognosis, making it suitable for conservative treatment." (PMID 40356755, 2025). "In the TCGA analysis, the ultra-mutated POLE group comprised 6.4% low-grade endometrioid carcinomas and 17.4% high-grade endometrioid carcinomas." (PMID 39062983, 2024). "POLE mutations are indeed significantly more frequent in high-grade endometrioid carcinoma (12.1%) than in low-grade endometrioid carcinoma (6.2%)." (PMID 36232987, 2022). "In fact, the PORTEC-3 study showed that patients with endometrioid carcinoma and a POLE mutation had excellent prognoses." (PMID 36431242, 2022). "Molecular classification is likely to be of particular value in high‐grade endometrioid carcinomas by picking out the POLE‐mutated (good actors) and the copy‐number high (poor actor) neoplasms." (PMID 34669206, 2021). "Of the grade 3 endometrioid carcinomas, those with POLE mutations were less likely to have risk factors necessitating adjuvant treatment than those with low tumor mutational burden." (PMID 33256706, 2020). "We propose to validate and develop the feasibility of using BaseScope, an in situ hybridization (ISH) assay, for the detection of POLE mutations in high-grade endometrioid carcinomas (EC)." (PMID 31552169, 2019). "It is our clinical practice to subject cases with ambiguous or ‘mixed’ morphology to MMR testing and occasionally POLE mutation testing, which may render an integrated diagnosis of MMRd or POLE‐mutated endometrioid carcinoma." (PMID 34596362, 2022). "Gynecological pathologists agree that POLE-mutant ECs with a serous morphology and immunophenotype should be deemed as endometrioid carcinomas." (PMID 36232987, 2022). "Because these cases are associated with ultra-mutated profiles and indolent behavior, designating them as CS does not reflect their true biology because POLE-mutated endometrioid carcinomas often show areas of low-grade atypia inconsistent with the definition of a CS." (PMID 39220645, 2024). "POLE mutation analysis may not be necessary in typical low‐grade endometrioid carcinomas since POLE mutations are not common in this group and these neoplasms would not qualify for adjuvant therapy unless they are advanced stage at diagnosis." (PMID 34669206, 2021).
melanoma (21 papers, 2016 to 2025). A malignant, usually aggressive tumor composed of atypical, neoplastic melanocytes. "Several other mutations were found that are very uncommon in melanomas and are of uncertain meaning, such as POLE mutations, which are well-characterized in other solid tumors." (PMID 35159047, 2022). "The germline variants of BRCA2, POLE, WRN, FANCI, PALB2, and RAD54B genes, involved in DNS repair mechanisms, have been implicated in rendering melanoma patients more susceptible to tumor progression and affecting their response to treatments." (PMID 39795882, 2024). "In their analysis, they observed that high TMB was only associated with better survival in the case of MSI- or POLD (POLE or POLD1)-mutated tumors, or in cancers highly related to environmental carcinogens (head and neck, lung, and melanoma)." (PMID 37108755, 2023). "For example, melanoma and non-small cell lung carcinomas frequently have high TMB but dMMR, MSI-high or POLE mutations are rare in these tumors, indicating other mechanisms can contribute to increased TMB." (PMID 32393302, 2020). "A similar trend was seen in melanoma, within SLX4, POLE, BRCA1, FANCD2, and ERCC6-mutated tumors containing a significantly higher mutational burden than overall melanoma." (PMID 27004405, 2016). "As expected, we found that (both primary and metastatic) melanomas were mainly characterized of signatures SBS7a/b (exposure to UV light), SBS1 (spontaneous deamination of 5-methylcytosine; clock-like), SBS5 (clock-like) and SBS10b (POLE/POLD1 mutations)." (PMID 36389735, 2022). "The identified studies indicated that POLE and POLD1 mutations are biomarkers for immunotherapy across multiple cancer types, and BRAF mutation can improve antitumor activity of immunotherapy in melanoma." (PMID 34211853, 2021). "Interestingly, elevated POLE expression predicts poorer outcome marker in renal cancer and melanoma patients." (PMID 31533246, 2019). "Here, our aim was to investigate whether patients in the Hungarian melanoma cohort (n = 17) with increased risk carry any pathogenic or likely pathogenic germline variants of the BRCA2, POLE, WRN, FANCI, PALB2, and RAD54B genes associated with melanoma survival and response to therapy." (PMID 39795882, 2024). "Thus, it appears that CTCFL mutations are often produced by underlying MSI or POLE or POLD1 defects in both cancers commonly associated with these defects (colorectal and endometrial) and in other cancers less commonly associated with them (melanoma)." (PMID 30275357, 2018). "Notably, the canine oral melanomas in our series also lacked SF3B1 and GNAQ mutations, and no mutations in POLE, PTPRD, or DMXL2 were found, suggesting that these canine cancers may not represent a faithful genetic model for the subset of human mucosal melanomas with mutations in these genes." (PMID 30664638, 2019).